CACNA2D1 (calcium voltage-gated channel auxiliary subunit alpha2delta 1)
Diseases named in the same sentence as CACNA2D1 in open-access papers (continued):
Sharing a sentence is not in itself a finding about the gene and the disease.
schizophrenia (2 papers, 2012 to 2020). A major psychotic disorder characterized by abnormalities in the perception or expression of reality. "Within a Swedish population, a disruptive (frameshift) variant in CACNA2D1 has been identified in an exome sequence of schizophrenia patients." (PMID 32607809, 2020). "Highest downregulation was seen for Cacna2d1, a gene that has been associated with schizophrenia." (PMID 23251410, 2012).
arrhythmogenic right ventricular cardiomyopathy (1 paper, 2024). "Moreover, we found that the expressions of ACTN3, cacna2d1, and TGA2, all associated with arrhythmogenic right ventricular cardiomyopathy, were considerably altered, which explains cardiac defects in some patients." (PMID 39619318, 2024).
attention deficit hyperactive disorder (1 paper, 2021). "Furthermore, our review has revealed CACNA1A, CACNA1C and CACNA2D1 as the candidate genes for attention deficit hyperactive disorder." (PMID 33985586, 2021).
Bovine mastitis (1 paper, 2016). INFLAMMATION of the UDDER in cows. "The CACNA2D1 gene encodes the alpha 2/delta subunit which is an accessory part of the voltage-gated calcium channel family (e.g., LTCC) and considered to be an important candidate protein influencing bovine mastitis." (PMID 26916791, 2016).
cardiac hypertrophy (1 paper, 2020). "Additionally, a long non-coding RNA related to cardiac hypertrophy, Chaer1, and genes related to hereditary arrhythmic disorders, including Ank2, Gpd1l, and Cacna2d1, were downregulated in the Rbm20S637A/S637A mice." (PMID 33110103, 2020).
Cerebellar atrophy (1 paper, 2022). Cerebellar atrophy is defined as a cerebellum with initially normal structures, in a posterior fossa with normal size, which displays enlarged fissures (interfolial spaces) in comparison to the foliae secondary to loss of tissue. "Individuals with biallelic CACNA2D1 or CACNA2D2 variants all have corpus callosum hypoplasia, while patients with CACNA2D1 variants show progressive cerebral atrophy whereas subjects harbouring CACNA2D2 variants have cerebellar atrophy." (PMID 35293990, 2022).
colon cancer (1 paper, 2025). "Similarly, CACNA2D1 depletion resulted in decreased colon cancer cell proliferation and migration, while also regulating fibroblast activities to influence the tumour microenvironment." (PMID 40429844, 2025).
keratoconus (1 paper, 2025). A degenerative, structural disorder of the eye, characterized by a cone-shaped protrusion of the cornea. "In the corneal samples of patients with keratoconus, calcium voltage-gated channels including CACNA1C, CACNA1G, CACNA2D1, and CACNA2D4 were found to be down-regulated that could be indicative of reduced cell proliferation as observed in keratoconus." (PMID 39420106, 2025).
Malignant hyperthermia (1 paper, 2014). Malignant hyperthermia is characterized by a rapid increase in temperature to 39-42 degrees C. Malignant hyperthermia may occur in response to either inhalational anesthetics such as halothane, to muscle relaxants such as succinylcholine, or to exercise. "However, CACNG1, CACNB1 and CACNA2D1 encode for subunits of the DHPR calcium channel, which is in direct contact and regulating RYR1 in skeletal muscle, and one mutation in the channel subunit CACNA1S of DHPR was linked to malignant hyperthermia." (PMID 25353622, 2014).
medulloblastoma (1 paper, 2020). A malignant, invasive embryonal neoplasm arising from the cerebellum. "Moreover, activated NK cells were positively correlated with GLI2 (p = 0.020, r = 0.318) and ELAVL3 (p = 0.020, r = 0.317) expression, and resting mastocyte cells were significantly correlated with CACNA2D1 expression (p = 0.026, r = 0.303) in SHH medulloblastomas." (PMID 32508873, 2020).
nicotine dependence (1 paper, 2024). Physical and psychological dependence on nicotine. "Like CACNA2D2 and CACNA2D3 have been reported as GWAS candidates associated with nicotine dependence, CACNA2D1 has been involved in increased presynaptic NMDAR activity associated with hyperalgesia following chronic morphine." (PMID 38338915, 2024).
non-small cell lung carcinoma (1 paper, 2025). A group of at least three distinct histological types of lung cancer, including non-small cell squamous cell carcinoma, adenocarcinoma, and large cell carcinoma. "In addition, CACNA2D1 has also been identified as a cancer stem cell marker for non-small-cell lung cancer and has been implicated in radiotherapy resistance through DNA damage repair regulation." (PMID 40429844, 2025).
Obesity (1 paper, 2023). Accumulation of substantial excess body fat. "Next, we designed and unilaterally injected AAV-hSyn-DIO-Cacna2d1-pA and AAV-hSyn-DIO-eGFP (1:1) into the right-lateral region of the vlPAG of DIO Gad2-Cre mice to overexpress CACNA2D1 in HFD-induced obesity mice." (PMID 37910621, 2023). "Cacna2d1 in the vlPAG GABAergic cells is identified as a potential target for treatment of obesity." (PMID 37910621, 2023). "Overexpressing CACNA2D1 in vlPAG GABAergic cells of DIO mice rescued enhanced mIPSCs and calcium response, reversed obesity, and therefore presented here as a potential target for obesity treatment." (PMID 37910621, 2023).
peripheral nerve injury (1 paper, 2024). Injury to a peripheral nerve. "Reduced HDAC2 occupancy at the Cacna2d1 promoter is involved in peripheral nerve injury-induced transcriptional activation of Cacna2d1 in the DRG." (PMID 39357831, 2024).
viral infection (1 paper, 2023). "To determine how fast AAV-Cacna2d1 viral infection can increase the expression level of CACNA2D1 in DIO mice, we explored the mRNA levels of Cacna2d1 1 day and 3 days after bilaterally injecting AAV-DIO-Cacna2d1 into the vlPAG brain region of DIO Gad2-Cre mice by RNA scope." (PMID 37910621, 2023).
tumor (16 papers, 2014 to 2025). "The high expression levels of PBX3 and CACNA2D1 have been validated to be associated with tumor-initiating-cell (TIC) properties in the cell clone from the recurrent tumor." (PMID 32205176, 2019). "To assess the importance of CACNA2D1 in NPC tumour development, we selected a cell line, C666, with the strongest expression of CACNA2D1 to conduct the functional experiment." (PMID 40429844, 2025). "To confirm that CACNA2D1 is specifically expressed in the NPC tumour cells, we clinically examined the expression level of CACNA2D1 using GeoMx digital spatial profiling (DSP)." (PMID 40429844, 2025). "The upregulation of CACNA2D1 likely increases calcium signalling in regulating these transcription factors and signalling pathways to promote tumour cell growth." (PMID 40429844, 2025). "In vitro and in vivo functional assays confirmed that CACNA2D1 regulates tumour cell viability, migration, and tumour growth." (PMID 40429844, 2025). "Immunohistochemistry (IHC) staining of CACNA2D1 was performed in clinical NPC patients to examine the expression of CACNA2D1 in matched normal and tumour regions scored by a pathologist." (PMID 40429844, 2025). "We then explored the relationship between PRLR, CACNA2D1, and tumor immunity by looking at tumor immune cell infiltration and immune checkpoints." (PMID 36556307, 2022). "The overexpression of CACNA2D1, JUN, GNG4, NGF, MYC, and MAPK4K4, components of the MAPK pathway, is associated with tumor aggressiveness and chemotherapy resistance." (PMID 36344487, 2022). "A retrospective study showed that positive expression of Cacna2d1 was significantly associated with advanced FIGO stage (P < 0.001), histological subtype (P = 0.017) and tumor differentiation (P = 0.015)." (PMID 32646427, 2020). "CACNA2D1(calcium voltage-gated channel auxiliary subunit alpha2delta 1) genes was critical for HCC TIC (tumor initiating cell) stemness and was predictive of poor prognosis for HCC patients." (PMID 29554896, 2018). "We also validated the elevated expression of CACNA2D1 in NPC tumours from patient samples." (PMID 40429844, 2025). "In the images, NPC tumour regions show expression of CACNA2D1 at the transcript level." (PMID 40429844, 2025). "Knocking out CACNA2D1 resulted in lower cell viability and reduced tumour formation in mice." (PMID 40429844, 2025). "These mice were dissected at the end of week 4, and the mouse tumours were IHC stained with CACNA2D1 to confirm the KO efficiency, confirming that CACNA2D1 may provide tumour progression capability." (PMID 40429844, 2025). "All these data pinpoint the specific expression of CACNA2D1 in NPC tumours." (PMID 40429844, 2025). "Functionally, CACNA2D1 was found to be mainly involved in myofibrillar composition, adhesive spots, and muscular structure development, and cytoskeleton-dependent intracellular transport and the cytoskeleton were all related to tumor immunity." (PMID 36556307, 2022). "In summary, these results suggested that the low expression of CACNA2D1 in BC may affect the clinical prognosis of BC patients by down-regulating the abundance of tumor immune infiltrating cells." (PMID 36556307, 2022). "Functional studies demonstrated that the mouse tumour size shrank by one-third upon the depletion of CACNA2D1, and there was an 85% reduction in cancer cell growth through the blockage of enhancers, while the presence of CACNA2D1 conferred a survival advantage during NPC tumour development." (PMID 40429844, 2025). "Indeed, a significant two-fold reduction in metabolic activity was exhibited in KO cells at both 48 and 96 h (p-value < 0.0001), implying that CACNA2D1 could increase tumour cell proliferation." (PMID 40429844, 2025). "Therefore, we were led to assume that CACNA2D1 might be related to tumor immunity." (PMID 36556307, 2022). "High expression levels of CACNA2D1 in epithelial ovarian cancers were significantly correlated with histological subtypes, advanced FIGO stages and tumor differentiation." (PMID 31827401, 2019).
tumor (continued). "Three genes (CACNA1D, CACNA2D1, and CACNA2D2) coding for the α subunit of voltage-dependent Ca2+ channels were down-regulated in tumor tissues." (PMID 24466154, 2014). "Additionally, CACNA2D1 knockout in NPC cells resulted in decreased cell viability and a reduced tumour volume in mice." (PMID 40429844, 2025). "But the mRNA level of CACNA2D1 was not significantly altered between tumor and normal tissues, and did not correlate with the patients’ survival time as well (data not shown)." (PMID 34611550, 2021). "With an equal amount of the cells administered subcutaneously to immunodeficient BALB/cAnN-nu (nude) mice via continuous monitoring for about four weeks, we found that the tumour size of WT mice grew significantly after week 1, by at least double, compared to the mice that did not express CACNA2D1." (PMID 40429844, 2025). "Ra cells were able to initiate tumor formation, whereas under the same condition, no tumorigenicity was detected in the other three samples, which is consistent with the up-regulation of TIC-associated markers in Ra, i.e., CACNA2D1 and PBX3." (PMID 32205176, 2019). "Humanised mouse models co-engrafted with NPC tumours with human immune system components or NPC organoids or spheroids in vitro 3D co-cultured with fibroblasts, immune cells, and endothelial cells could be utilised in the future for investigating the metastatic behaviour of CACNA2D1." (PMID 40429844, 2025).
cancer (8 papers, 2019 to 2025). A tumor composed of atypical neoplastic, often pleomorphic cells that invade other tissues. "Elevated CACNA2D1 expression has been reported to be associated with poor prognosis in several types of cancer." (PMID 37175550, 2023). "The observation of enhancer infestation in CACNA2D1 and other candidate genes highlights the importance of enhancer dysfunction in cancer." (PMID 40429844, 2025). "Multiple Ca2+-handling proteins, including CACNA1D, CACNA2D1, TRPV4, TRPV1, TRPM4, MCU, and RyR1, exhibit cancer-associated overexpression or functional changes, correlating with poor prognosis and aggressive disease features." (PMID 41226294, 2025). "Elevated expression of CACNA2D1 and SLC8A1 genes was linked to EC progression, as reflected by cancer stage and grade, and correlated with poorer prognosis." (PMID 41226294, 2025). "Through a combination of multi-omics analyses and AI-driven screening, we identified CACNA2D1 as a novel cancer-cell-specific therapeutic target in NPC." (PMID 40429844, 2025). "Suppression of BRD4-bound enhancers resulted in decreased cell viability, suggesting that exploiting H3K27ac provides CACNA2D1 with a cancer cell growth advantage and therefore promotes cancer progression." (PMID 40429844, 2025). "We found several overlapping DEmRNAs that were involved in multiple pathways, such as SLC8A1, CAMK2B, and CACNA2D1, and have been demonstrated to play important roles in cancer pathogenesis." (PMID 31827401, 2019). "Compared with that in the normal tissues, the expression of CD24, CD90, EpCAM, CACNA2D1, and CD133 was found highly expressed in the cancer tissues." (PMID 33707423, 2021). "The ITPR1 variant could be altering the inflammatory and immune response involved in the pathogenesis of conditions such as cancer since this function is enriched in the MetaScape analysis by this and other candidate genes (FOXM1, CACNA2D1 and NTRK1)." (PMID 37175550, 2023).
neurodevelopmental disorder (2 papers, 2022 to 2024). A behavioral and cognitive disorder with onset during the developmental period that involves impaired or aberrant development of intellectual, motor, or social functions. "An indirect interaction between SCN9A and CACNA2D1 may exist through LAT1 (SLC7A5) as a common regulator of both; indeed, CIP can be present in patients with CACNA2D1 variants as a part of a more syndromic and severe neurodevelopmental disorder." (PMID 39156962, 2024). "Thus, biallelic loss-of-function variants in CACNA2D1 underlie the severe neurodevelopmental disorder in these two patients." (PMID 35293990, 2022).
neurological disorder (1 paper, 2015). "However, as a note of interest, these CNVs included the NDUFB3, NIF3L1, PPEF2, CACNA2D1 and GPC5 genes, which are expressed in the brain and/or have been implicated in neurological disorder." (PMID 25585696, 2015).
CACNA2D1 also shares sentences with these, for which no sentence is quoted: Intellectual disability (7 papers); Arrhythmia (2); depression (2); developmental and epileptic encephalopathy (2); early repolarization syndrome (2); epithelial ovarian cancer (2); hepatocellular carcinoma (2); primary open angle glaucoma (2); prostate carcinoma (2); Timothy syndrome (2); Ventricular arrhythmia (2); asthma (1); bacterial diseases (1); bipolar disorder (1); bladder cancer (1); brain disorder (1); cardiac arrhythmias (1); cerebellar ataxia (1); cervical cancer (1); coronary artery stenosis (1); Coronary Heart Disease (1); diabetes (1); diabetic cardiomyopathy (1); fibrosarcoma (1); Hearing impairment (1); Hyperinsulinemia (1); hypertrophic cardiomyopathy (1); idiopathic ventricular fibrillation (1); ischemic stroke (1); liver cancer (1).
A further 13 diseases each share a sentence with CACNA2D1 in 1 paper.